SMAD7 (SMAD family member 7)
Diseases named in the same sentence as SMAD7 in open-access papers (continued):
Sharing a sentence is not in itself a finding about the gene and the disease.
glioblastoma (13 papers, 2009 to 2025). The most malignant astrocytic tumor (WHO grade IV). "Ad-Smad7 also inhibited activation of the BRE-luciferase reporter in these glioblastoma cell lines for both TGF-β and BMP7 stimulation, while additionally inhibiting TGF-β mediated activation of the CAGA12-luciferase reporter." (PMID 39724753, 2024). "For example, HERC3 was reported to mediate the ubiquitination and the degradation of SMAD7 in glioblastoma." (PMID 34195188, 2021). "For instance, HERC3 was reported to be a tumor suppressor via regulating SMAD7 in glioblastoma." (PMID 34195188, 2021). "The relevant research of HERC3 in terms of cancers is rare, HERC3 is once reported to mediate SMAD7 ubiquitination degradation and induce the autophagy-mediated EMT and chemoresistance in glioblastoma." (PMID 35064108, 2022). "And to our knowledge, HERC3 is only once reported to promote ubiquitination degradation SMAD7 and induces autophagy-mediated EMT in glioblastoma." (PMID 35064108, 2022). "In WT A-172 human glioblastoma cells, MRT199665 also inhibited TGFβ-induced expression of PAI-1 mRNA, as well as SMAD7 and connective tissue growth factor (CTGF) mRNAs." (PMID 31969556, 2020). "To further confirm this, we detected the PAI-1 and Smad 7 mRNA level in glioblastoma cells treated with TGF-β1, the data showed that PAI-1 mRNA was increased significantly in four cells treated with TGFb1 for 48 h, however Smad7 mRNA was not enhanced as highly and significantly as PAI-1 mRNA." (PMID 28912531, 2017).
hypertensive nephropathy (12 papers, 2013 to 2024). Kidney damage that results from chronically elevated blood pressure; complications include glomerular damage resulting in proteinuria and hematuria. "Under CKD conditions, loss of renal Smad7 is associated with activation of NF-κB signaling and severe renal inflammation as reported in hypertensive nephropathy and aristolochic acid-induced nephropathy." (PMID 32258028, 2020). "Therefore, in this study we determined the function and underlying mechanisms of Smad7 in ANG II-mediated hypertensive nephropathy through the use of Smad7 KO mice." (PMID 23301086, 2013). "Inversely, knockout of Smad7 promotes inflammation with more severe impairment of renal function in chronic aristolochic acid nephropathy, hypertensive nephropathy, and UUO kidney." (PMID 34360646, 2021). "The present study identified that Smad7 plays a protective role in ANG II-mediated hypertensive nephropathy." (PMID 23301086, 2013). "Smad7 as a downstream inhibitor of both pathways, could block Ang II-induced hypertensive renal disease in mice." (PMID 38345042, 2024). "Thus, deletion of Smad7 promotes, but overexpression of Smad7 inhibits angiotensin II-induced AT1-ERK1/2-Smad3-mediated hypertensive nephropathy." (PMID 34831368, 2021). "Mice lacking ACE2 developed more severe hypertension and hypertensive nephropathy, which was associated with a marked activation of the Smurf2-dependent Smad7 ubiquitin degradation pathway." (PMID 34831368, 2021). "Thus, deletion of Smad7 promotes but overexpression of Smad7 inhibits Ang II‐induced AT1‐ERK1/2‐Smad3‐mediated hypertensive nephropathy." (PMID 32971570, 2020). "Results from this study suggest that strategies that can increase Smad7 levels may have therapeutic potential for hypertensive nephropathy." (PMID 23301086, 2013). "Thus, the aim of this study was to investigate the role and regulatory mechanisms of Smad7 in ANG II-induced hypertensive nephropathy." (PMID 23301086, 2013). "Additionally, disruption of SMAD7 results in angiotensin II–mediated hypertensive nephropathy." (PMID 37707956, 2023). "However, the role of Smad7 in hypertensive nephropathy in response to ANG II remains unexplored." (PMID 23301086, 2013). "Thus, Smad7 plays a protective role in ANG II-induced hypertensive nephropathy." (PMID 23301086, 2013). "However, the role and mechanisms of Smad7 in hypertensive nephropathy remains unexplored." (PMID 23301086, 2013). "In vivo, overexpression of Smad7 attenuates fibrosis in different renal disease models including 5/6 nephrectomy, crescentic glomerulonephritis, UUO, chronic aristolochic acid nephropathy, and hypertensive nephropathy." (PMID 34360646, 2021).
atherosclerosis (11 papers, 2019 to 2024). A disease characterized by the build-up of fatty material and calcium deposition in the arterial wall resulting in partial or complete occlusion of the arterial lumen. "In both human atherosclerotic plaques and atherosclerosis patients, the SMAD7 promoter is hyper-methylated and it is positively related to homocysteine levels and carotid plaque scores." (PMID 38031118, 2023). "In summary, our findings suggest a new mechanism of vascular endothelial inflammation involving Smad7/IκBα signalling pathway in atherosclerosis." (PMID 33282009, 2020). "There was also increased DNA methylation of the SMAD7 promoter in the peripheral blood of atherosclerosis patients." (PMID 31649728, 2019). "Hcy also plays a role in the inflammatory response and DNA methylation disorder in atherosclerosis, activating NF-κB-mediated vascular inflammatory response in human umbilical VSMCs via promoting SMAD7 promoter hypermethylation in a dose and time-dependent manner." (PMID 38031118, 2023). "Smad7 was also downregulated in ApoE knockdown atherosclerosis models (p < 0.05)." (PMID 33872218, 2021). "Additionally, HCy promotes vascular inflammation and atherosclerosis through hypermethylation of the SMAD7 promoter." (PMID 32599677, 2020). "Thus, the SMAD7 promoter is hypermethylated in atherosclerosis patients and their atherosclerotic plaques, with a positive association with homocysteine levels." (PMID 31649728, 2019). "Smad7 is regarded as a downstream suppressive Smad in TGF-β signaling and participates in atherosclerosis by affecting a series of biological processes, including fibrosis and inflammation." (PMID 33872218, 2021). "This work demonstrated that MiR-200c-3p promoted ox-LDL-induced EndMT in HUVECs through SMAD7/YAP pathway, which may be important for the onset of atherosclerosis." (PMID 34525946, 2021). "Moreover, several target genes of miR-92a have been determined to be involved in the regulation of atherosclerosis and CAS, such as phosphatase and tensin homolog (PTEN), SMAD family member 7 (SMAD7) and fibroblast growth factor receptor substrate 2 (FRS2)." (PMID 32522208, 2020). "This review focuses on the role and mechanism of action of miR-26 in atherosclerosis, including the detection value of miR-26 and the potential development of drugs targeting its downstream genes, such as ACC1/2, COL1A1, CPT1A, FBP1, DGAT2, and SMAD7, to provide insight for drug development." (PMID 38195542, 2024). "However, the roles of macrophage-derived EVs carrying miR-503-5p in atherosclerosis via Smad7-Smurf1/Smurf2-TGF-β axis have not been investigated yet." (PMID 33872218, 2021).
keloid (11 papers, 2015 to 2025). An irregularly shaped, elevated mark on the skin caused by deposits of excessive amounts of collagen during wound healing. "It is upregulated in keloid tissues and directly targets Smad7, an inhibitory Smad protein, thereby reinforcing TGF-β/Smad2/3 signaling." (PMID 40980326, 2025). "In this study, we found that silencing circPTPN12 activates the Wnt signal pathway by regulating the miR-21-5p/SMAD7 axis, thus affecting the progression of keloid." (PMID 35068324, 2022). "This study reveals for the first time the mechanism of the effect of circPTPN12 on keloid formation, and the appearance of circPTPN12/miR-21-5p/SMAD7 axis also provides a reliable target for the treatment of keloid." (PMID 35068324, 2022). "Our results indicate that silencing circPTPN12 targets the miR-21-5p/SMAD7 axis and activates the Wnt signaling pathway, thus affecting the progression of keloid." (PMID 35068324, 2022). "The interaction of circPTPN12/miR-21-5p/SMAD7 axis in keloid can further reveal that circPTPN12 inhibits keloid formation." (PMID 35068324, 2022). "Other studies have revealed that asiaticoside can reduce the expression of the TGF-β receptor in keloid fibroblasts and increase the expression of Smad7 in a dose-dependent manner to inhibit the production of ECM protein in the extracellular matrix." (PMID 35646845, 2022). "Jialiang el al., which was the first study to demonstrate increased Smad4 expression and decreased Smad7 expression in keloids, proposed that Toll-like receptors (TLRs) exert contribute to keloidogenesis through TGF-β/Smad signaling." (PMID 33931723, 2021). "Smad7, a key negative regulatory smad, was reported to be downregulated in keloids, as well as other fibrotic tissues, such as the lung, liver and kidney." (PMID 27694104, 2016). "Ginsenoside Rg3 increased the expression of Smad7, which significantly inhibited the proliferation, migration, invasion, angiogenesis and collagen synthesis of human keloid fibroblasts (KFs) and suppressed angiogenesis and collagen accumulation in keloids through an ex vivo assay." (PMID 39866837, 2025). "In terms of mechanism, the circPTPN12/MiR-21-5p/SMAD7 axis plays a vital role during keloid formation, and a significant increase in circPDE7B has been observed in human keloid tissues and human KFBs, accompanied by miR-661 downregulation and FGF2 upregulation." (PMID 37993257, 2023). "Overexpression of Smad7 inhibits NK cell in keloids proliferation and migration." (PMID 37168863, 2023). "Taken together, we believe that silencing circPTPN12 promotes the proliferation, migration, invasion, and inhibition of apoptosis of keloid fibroblasts by targeting miR-21-5p/SMAD7 pathway and activating Wnt signaling pathway, thus promoting the formation of keloid." (PMID 35068324, 2022). "To further verify whether circPTPN12 regulates keloid formation through the miR-21-5p/SMAD7 axis, we co-transfected si-circPTPN12 and miR-21-5p inhibitors into keloid fibroblasts." (PMID 35068324, 2022). "In addition, we found that miR-21-5p suppressed the level of SMAD7 in keloid fibroblasts transfected with miR-21-5p mimics (P < 0.05)." (PMID 35068324, 2022). "In in vitro assays, we confirmed that silencing circPTPN12 could accelerate viability and suppress apoptosis of keloid fibroblasts via miR-21-5p/SMAD7 axis." (PMID 35068324, 2022). "Therefore, we determined that SMAD7 was the target of miR-21-5p in keloid." (PMID 35068324, 2022). "This suggested that the miR-21-5p/SMAD7 axis could regulate keloid progression." (PMID 35068324, 2022). "Consistent with previous reports by Li and others, SMAD7 may be a target for treating keloid." (PMID 35068324, 2022). "Indeed, miR-21-5p could be packed with circPTPN12 sponge, SMAD7 was downstream effect factor of miR-21-5p, and miR-21-5p inhibitors partially reversed the promoting effect of silencing circPTPN12 on keloid formation." (PMID 35068324, 2022).
keloid (continued). "Additionally, SMAD7, as a downstream target of miR-21-5p, was declined in keloids." (PMID 35068324, 2022). "Specifically, miR-21 promotes keloid fibrosis by downregulating SMAD7, thereby enhancing TGF-β/Smad signaling, and miR-199a-5p is downregulated in keloid tissue, with its restoration shown to inhibit keloid fibroblast proliferation and alter the cell cycle." (PMID 40980326, 2025). "For instance, hypermethylation of antifibrotic genes (e.g., SMAD7) and upregulation of pro-fibrotic microRNAs such as miR-21 and miR-199a enhance TGF-β signaling and collagen production in keloid fibroblasts." (PMID 40980326, 2025). "Additionally, treating keloid derived fibroblasts with INF-γ significantly increased the expression of Smad3 and Smad7 in a time and dose dependent manner." (PMID 26236109, 2015). "However, the involvement of circPTPN12/miR-21-5p/SMAD7 in keloid has not been elucidated." (PMID 35068324, 2022).
myocardial infarction (11 papers, 2018 to 2025). Gross necrosis of the myocardium, as a result of interruption of the blood supply to the area, as in coronary thrombosis. "In cardiac tissues, SMAD7 has shown antifibrotic and cardioprotective effects in models of myocardial infarction, hypertrophic obstructive cardiomyopathy, heart failure, and diabetic cardiomyopathy." (PMID 40745212, 2025). "Another study revealed that, while macrophage-specific Smad7 induction occurs after myocardial infarction, its functional role in repair is limited compared to the profound antifibrotic impact of myofibroblast-specific Smad7." (PMID 40745212, 2025). "miR-21 is also upregulated in the infarcted zone after myocardial infarction and promotes cardiac fibrosis by inhibition of the “Smad7” pathway." (PMID 32537679, 2020). "Overexpression of miR-21 promotes cardiac fibrosis after myocardial infarction by directly targeting Smad7." (PMID 29760746, 2018). "Additionally, miR-96 promotes myocardial infarction-induced cardiac fibrosis through the Smad7/Smad3 pathway." (PMID 41154662, 2025). "miR-15b-5p targets SMAD Family Member 7 (SMAD7), Notch Receptor 2 (NOTCH2), an important player in the regeneration and cardiac repair post myocardial infarction, and Autophagy Related 9A (ATG9A)." (PMID 38132140, 2023). "High levels of miR-21 could contribute to fibrosis progression and fibroblast activation in myocardial infarction targeting molecules as PTEN, Smad7, and TGF-β receptor III." (PMID 34574061, 2021).
osteosarcoma (11 papers, 2015 to 2022). A usually aggressive malignant bone-forming mesenchymal neoplasm, predominantly affecting adolescents and young adults. "In this context, we demonstrated that Smad7 overexpression in osteosarcoma cells blocks their ability to produce RANKL, a cytokine that plays a central role in osteoclast differentiation and activation." (PMID 27827889, 2016). "RNA-seq analysis of MEFs and human osteosarcoma cells further shows that Smad7Δ arises due to novel splicing and that we have uncovered an alternately spliced form of Smad7." (PMID 27536941, 2016). "Using a xenograft murine model of osteosarcoma, we specifically demonstrated that Smad7 overexpression slows primary tumor growth." (PMID 27827889, 2016). "Finally, in vivo experiments demonstrated that blocking TGF-β signaling by Smad7 overexpression in osteosarcoma cells or treating mice with the ALK5 inhibitor SD-208, reduces expression of both the endothelial marker CD146 and PDGF." (PMID 29761075, 2018). "Indeed, in a xenograft murine model of osteosarcoma using human HOS or SaOS2 cells, Smad7 overexpression in tumor cells inhibited the tumor-associated bone destruction by both promoting ectopic bone formation and preventing trabecular bone osteolysis." (PMID 29761075, 2018). "In addition, we recently demonstrated that blocking TGF-β signaling by overexpression of Smad7 in osteosarcoma cells inhibits the expression and release of osteolytic factors such as RANKL and IL-11 by tumor cells." (PMID 26015407, 2015). "Similarly, SMAD7 functions as an important target gene for miR-181c in osteosarcoma cells." (PMID 35782228, 2022). "Dysregulation of miR-181c also contributes to the aggressiveness of osteosarcoma and regulation of TGF-β signaling through targeting SMAD family member 7 (SMAD7), which negatively regulates TGF-β." (PMID 34483928, 2021). "In vivo experiments, using molecular (overexpression of the Smad inhibitor, Smad7) and pharmacological (SD-208 and/or halofuginone) approaches, have demonstrated that TGF-βs affect the development of lung metastases in osteosarcoma." (PMID 29761075, 2018). "More recently, using molecular (over-expression of the inhibitor Smad, Smad7) and pharmacological (SD-208 and/or halofuginone) approaches, we clearly demonstrated that TGF-βs affect osteosarcoma tumor growth and lung metastatic development." (PMID 27827889, 2016). "Although we have not observed an effect of Smad7 on the ability of TGF-β to stimulate the MAPK pathway in osteosarcoma cells (suggesting a crucial role of the TGF-β/Smad cascade in osteosarcoma progression), the role of TGF-β/MAPK pathways cannot be ruled out." (PMID 27827889, 2016). "Of note, in contrast to Smad7, the effects of halofuginone appear to be mainly due to its pro-apoptotic properties in osteosarcoma, regardless of its ability to inhibit the TGF-β signaling pathway." (PMID 27827889, 2016).
bladder cancer (10 papers, 2019 to 2025). "Aberrant nuclear export of Circular RNA NCOR1 (circNCOR1) underlies small mothers against decapentaplegic 7 (SMAD7)-mediated lymph node metastasis of bladder cancer." (PMID 38023219, 2023). "In vitro knockdown of eRNA SMAD7 can suppresse tumorigenesis and progression of bladder cancer by CRISPR-Cas13a." (PMID 35568893, 2022). "In conclusion, knockdown of SMAD7 attenuated the effects of estrogen on bladder cancer." (PMID 33282916, 2020).